AQP4 (aquaporin 4)
Diseases named in the same sentence as AQP4 in open-access papers (continued):
Sharing a sentence is not in itself a finding about the gene and the disease.
autoimmune disease (continued). "Of those ten anti-AQP4-IgG+ patients, three had two and one had even four additional autoimmune diseases." (PMID 33776892, 2021). "Ten of the 34 anti-AQP4-IgG+ patients (29%) had at least one additional autoimmune disorder as compared to only two of the 29 anti-AQP4-IgG− patients (7%)." (PMID 33776892, 2021). "The development of a mouse model with a neuro-autoimmune disease that targets AQP4 has been a challenge." (PMID 32503977, 2020). "In MOG-EM, the frequency of coexistent autoimmune diseases seems to be lower than reported for AQP4-Ab positive patients." (PMID 30405519, 2018). "Neuromyelitis optica (NMO) is an autoimmune disease associated with NMO immunoglobulin G (NMO-IgG), an antibody that selectively binds to the aquaporin-4." (PMID 29311561, 2018). "Since NMO is an antibody‐mediated autoimmune disease of the CNS, we next studied the antigen‐specific serum response upon immunization with AQP4 protein." (PMID 28058717, 2017). "Testing of AQP4-Ab is essential and is the most important test in the diagnostic work-up of suspected NMO, and helps to distinguish NMO from other autoimmune diseases." (PMID 24272588, 2014). "Fourth, stringent inclusion/exclusion criteria (e.g., inclusion of AQP4-IgG seropositive patients, exclusion of those with comorbid autoimmune disorders and use of lipid-lowering agents) resulted in a relatively small sample size, diminishing statistical power." (PMID 40735294, 2025). "Anti-AQP4 autoantibodies may also target AQP4 components, as observed in the CNS autoimmune disease neuromyelitis optica (NMO)." (PMID 41373677, 2025). "However, current NMOSD animal models are mainly focused on the AQP4-IgG antibody, neglecting the potential influence of other autoimmune diseases and antibodies on the disease’s onset and progression." (PMID 39628487, 2024). "Immunofluorescence analysis showed that treatment with hsAQP4-IgG, but not hsCtrl-IgG or LPS, lead to the internalization and degradation of AQP4 in astrocytes, which is a hallmark of NMO pathology that distinguishes NMO from the autoimmune disease multiple sclerosis." (PMID 38242900, 2024). "Co-existing autoimmune disorders are less common in MOGAD than in AQP4+ NMOSD, but NMDAR antibodies may occasionally be positive in patients with MOGAD." (PMID 37789888, 2023). "It has been reported that AQP4‐Ab was detectable in 84.6% patients with SLE and NMO or LETM/rON and in 62.5% patients with other CTD and NMO or LETM, which showed the coexisting relationship between other autoimmune diseases and AQP4‐Ab‐positive NMOSD patients." (PMID 33319460, 2021). "To verify whether coexisting autoimmune disease may exacerbate experimental autoimmune MG, we tested whether active immunization with AQP4 peptides or passive transfer of NMO-Ig can affect the severity of EAMG." (PMID 29951558, 2018). "This review is a good opportunity to compile recent knowledge and could contribute to the therapeutic treatment of autoimmune diseases through strategies targeting AQP4." (PMID 27517922, 2016). "Specialized tests, e.g., toxin screens and serum B12 for toxic optic neuropathy; markers for autoimmune diseases; antibody to aquaporin-4 and MRI spine in NMO; genetic analysis for mitochondrial mutation in cases of Leber’s hereditary optic neuropathy, are required in suspected conditions." (PMID 21350281, 2011). "The scenario of AQP4-specific activation of B and T cells is similar in autoimmune diseases." (PMID 18510734, 2008). "According to DO enrichment analysis, the AQP4-ON group was mainly associated with atherosclerosis, arteriosclerotic cardiovascular disease and arteriosclerosis, while the MOG-ON group was associated with Alzheimer’s disease, hypersensitivity reaction type II disease and rheumatoid arthritis." (PMID 36969199, 2023).
autoimmune disease (continued). "Treatment for the autoimmune disease MS has been tested in three phase I clinical trials, one completed, where two different subsets, Dex-tolDCs loaded with myelin peptides or aquaporin-4-derived peptides (AQP4) and VitD3-tolDCs loaded with several myelin peptides, were tested." (PMID 34360736, 2021). "The neurological and physical examination should focus not only on the primary symptoms, but also on disease indicators that could suggest alternative diagnoses or concomitant autoimmune disorders, which are frequently present in patients with AQP4-Ab-positive NMO." (PMID 24272588, 2014). "Overall, since AQP4-IgG originates peripherally, NMOSD is regarded as an autoimmune disease peripherally antibody-mediated and manifested in the CNS." (PMID 40568579, 2025). "AQP4‐NMOSD patients had more multiple comorbidities (50%, n = 81/161) than MOGAD (25%, n = 5/20, p = 0.03) and more autoimmune disorders (AID) (40.4%, n = 65) than MOGAD (20%, n = 4, p = 0.09) and DN‐NMOSD (none, p = 0.004)." (PMID 40485599, 2025). "This further highlights the role of complement in AQP4-IgG–mediated disease and diminishes the importance of complement activation in MOG-IgG–mediated autoimmune disease." (PMID 36414427, 2023). "We describe a case of a male Chinese patient who presented simultaneously with two distinct autoimmune diseases: anti-NMDAR encephalitis with positive NMDAR antibodies in the CSF and NMOSD with AQP4-IgG-seropositivity." (PMID 35527314, 2022). "In 2004, with the discovery of a disease specific NMO-IgG antibody against the AQP4 water channel (AQP4-IgG), NMO was considered as a different autoimmune disease entity." (PMID 35054412, 2021). "The two leading additional autoimmune disease were autoimmune thyroiditis in 4 and systemic lupus erythematosus (SLE) in five of the anti-AQP4-IgG+ patients." (PMID 33776892, 2021). "Neuromyelitis optica (NMO) is an autoimmune disease in which a specific biomarker named NMO-IgG and directed against aquaporin-4 (AQP4) has been found." (PMID 23710199, 2013). "Additional autoimmune diseases are unlikely to significantly affect clinical or visual outcomes in early attacks in patients with AQP4-NMOSD and MOGAD." (PMID 40495001, 2025). "Second, thyroperoxidase antibodies and other autoantibodies are detectable in up to half of AQP4-IgG-seropositive NMOSD patients, with approximately one-third exhibiting comorbid autoimmune disorders such as thyroiditis, systemic lupus erythematosus, or Sjögren’s syndrome." (PMID 40735294, 2025). "In the cases of AQP4-IgG seropositive NMOSD who have recurrent episodes and are comorbid with other autoimmune disorders, inebilizumab may be a good choice." (PMID 38899058, 2024). "In the current study, we sought to expand cross-disease autoantibody exploration to include four validated neurologic autoantibodies (MOG, AQP4, AChR, and MuSK) in nonneurologic autoimmune diseases." (PMID 30824481, 2019). "A comprehensive analysis of AQP4 and OPN together might shed light on the treatment of autoimmune diseases in the CNS." (PMID 27517922, 2016). "It is possible that exposure to epitopes that resemble human AQP4 from exogenous sources such as plants may play a role in the etiology of RRMS and possibly other autoimmune disorders." (PMID 26290755, 2015). "NMO-IgG has been found in patients with various infections and autoimmune disorders, as well as neoplastic, conditions not typically consistent with induction of the immune system against CNS AQP4." (PMID 18510734, 2008). "AQP4-NMOSD often coexists with various autoimmune diseases (AID), particularly systemic conditions, such as Sjogren’s syndrome and systemic lupus erythematosus, as well as organ-specific autoimmune disorders like autoimmune thyroid disease and myasthenia gravis." (PMID 40495001, 2025).
autoimmune disease (continued). "Co-existing autoimmune diseases are observed in up to 7–10% of MOGAD patients, with Sjogren syndrome, rheumatoid arthritis, ulcerative colitis, thyroid disorder, psoriasis, and NMDAR encephalitis being commonly reported, but the frequency appears to be lower than that in AQP4+ NMOSD." (PMID 37789888, 2023). "Therefore, in some patients detectable anti-AQP4-IgG titers may signify the co-occurrence of NMOSD and additional autoimmune disease." (PMID 33776892, 2021). "NMOSD is a pretty new umbrella term used to include aquaporin-4 IgG antibodies AQP4-IgG seropositive patients with limited forms of NMO, those with typical NMO who have cerebral, diencephalon and brainstem lesions and AQP4-IgG seropositive patients with coexisting autoimmune diseases." (PMID 28109254, 2017). "Sjögren's Syndrome is an autoimmune disease characterized by inadequate tear and saliva production and a lymphocyte infiltration of exocrine glands, especially the lacrimal and salivary glands, which express AQP 5 on the apical membrane and AQP4 on lateral membranes." (PMID 18510734, 2008). "Interestingly, a recent study in AQP4-knockout mice found that experimental autoimmune encephalomyelitis (EAE) was attenuated in comparison to wild-type mice, which implicates AQP4 as a novel disease determinant of the severity of EAE and likely other autoimmune disorders of the CNS." (PMID 22363840, 2012). "Screening for autoimmune diseases, including MOG and AQP4 antibodies, and metabolic diseases were negative." (PMID 38138047, 2023). "Aquaporin-4 is the first target antigen of autoimmune diseases of the CNS to be identified, but not all patients with NMODS have serum AQP4-IgG." (PMID 36385950, 2022). "Autoimmune disorders, including Bickerstaff’s, ADEM, NMO, and MS, were considered but deemed less likely due to atypical clinical and radiological features, as well as negative lab findings (anti-GM1, anti-GQ1, anti-MOG, anti-AQP-4, and oligoclonal bands)." (PMID 40135036, 2025). "Generally, our results do not support the hypothesis that patients with AQP4-seropositive LONMOSD show lower symptom severity, as has been reported in other autoimmune disorders." (PMID 26337073, 2015).
ischemic stroke (108 papers, 2010 to 2026). A stroke disorder caused by obstruction of blood flow to the brain, due to thrombotic (local blood clot formation) or embolic (due to a blood clot or other material traveling from another site) event. "Inhibition of AQP4 has been found recently as therapy targeting central nervous system edema post-injury, including attenuating cerebral edema associated with ischemic stroke and eventually promoting neurological recovery." (PMID 40360812, 2025). "Previous studies have demonstrated that AQP4 expression is associated with the development of brain edema following ischemic stroke." (PMID 41035004, 2025). "In the context of ischemic stroke, peri-infarct reactive astrocyte hyperplasia is commonly associated with AQP4 depolarization in the same region." (PMID 37695472, 2024). "Studies on AQP4-deficient (AQP4−/−) mice have shown that AQP4 facilitates cytotoxic edema while reducing vasogenic edema following ischemic stroke." (PMID 39457496, 2024). "Numerous studies highlight associations between alterations in AQP4 expression or localization and various central nervous system diseases, such as ischemic stroke, epilepsy, neuropathic pain, and glioblastoma." (PMID 39295943, 2024). "Altered expression and / or polarization of AQP-4 have been linked, both in experimental models and in humans, to impaired water homeostasis in neurological diseases such as ischemic stroke and neurotrauma, including bTBI." (PMID 37674234, 2023). "A study on brain edema in AQP4-deficient mice after a focal ischemic stroke induced by middle cerebral artery occlusion illustrated that AQP4 deletion improved neurological outcomes." (PMID 35890028, 2022). "For ischemic stroke and other multiple CNS diseases, peri-infarct reactive astrogliosis is usually accompanied by loss of AQP4 polarization in the same area." (PMID 35592320, 2022). "By causing more brain edema, AQP4 exacerbates cerebral ischemia in the rat model of ischemic stroke." (PMID 36710937, 2022). "The beneficial effect of AQP4 deficiency after ischemic stroke in mice was shown when cytotoxic edema was the predominant pathophysiological mechanism." (PMID 34502395, 2021). "This pathophysiological process is in line with evidence demonstrating that AQP4-deficient mice and wild types treated with AQP4 inhibitors progress with less cerebral edema after ischemic stroke." (PMID 34483842, 2021). "An overview of the literature suggests that prominent phenotypes associated with the AQP4-model mainly emerge in pathological conditions, such as induced meningitis or ischemic stroke." (PMID 30557661, 2019). "AQP4 gene knockout mice experiments also proved that AQP4 loss reduced the cytotoxic edema caused by ischemic stroke." (PMID 30233364, 2018). "The onset of vasogenic edema, which develops during hemorrhagic stroke and late stages of ischemic stroke, is associated with the upregulation of AQP4 channels." (PMID 27438832, 2016). "AQP4-deficient mice showed an improved neurological outcome after acute water intoxication and ischemic stroke." (PMID 27517922, 2016). "Mice deficient in AQP4 suffer less brain edema after an acute water intoxication and ischemic stroke." (PMID 24416250, 2014). "AQP4 is associated with cytotoxic edema during ischemic stroke." (PMID 37840921, 2023). "This suggests that AQP4 plays a role in oedema associated with ischemic stroke." (PMID 34843700, 2022). "The present study demonstrated that monotherapy and combination therapy of Emodin and GRb1 have a neuroprotective effect via the down-regulation of AQP4, which may be associated with reduction of cerebral edema caused by ischemic stroke." (PMID 30233364, 2018). "Although causative studies remain unperformed after neurotrauma, attenuated swelling of pericapillary astrocytic foot processes, decreased cellular edema, and reduced mortality were observed in AQP4-deficient mice after ischemic stroke or after acute water intoxication." (PMID 22815977, 2012).
ischemic stroke (continued). "One could assume that the DG-deficient mouse, due to the loss of perivascular AQP4, might similarly survive such water intoxication or ischemic stroke." (PMID 21501259, 2011). "In summary, while clinical studies link AQP4 to prognosis, edema severity, and genetic susceptibility, experimental models provide a deeper understanding of its biphasic role, regional variability, and therapeutic potential, highlighting both protective and pathological effects in ischemic stroke." (PMID 40564125, 2025). "Therefore, cerebrovascular diseases, such as subarachnoid hemorrhage and ischemic stroke, can cause AQP4 depolarization, expansion of the PVS, dysfunction in the drainage of MLVs and synaptic impairment, further disturbing the function of the glymphatic system and facilitating the progression of AD." (PMID 38270115, 2024). "However, after ischemic stroke, α-syntrophin and dystrophin are retained in perivascular membranes, indicating that other mechanisms must be responsible for the loss of perivascular AQP4." (PMID 35163040, 2022). "From a therapeutic perspective, microRNAs (miRNAs) play a key role in regulating AQP4 expression in astrocytes, offering new targeted strategies for the treatment of brain edema following ischemic stroke." (PMID 41451205, 2025). "By advancing the understanding of AQP4's dual role, this study contributes to the growing body of evidence supporting glymphatic system‐targeted therapies in ischemic stroke." (PMID 39927473, 2025). "Ischemic stroke rats exhibited a higher expression level of AQP4 than that of sham rats (p < 0.01), while silencing ATF3 in MCAO rats significantly downregulated the expression of AQP4 compared with MCAO or lv-NC rats (p < 0.01)." (PMID 40621504, 2025). "In the acute phase of ischemic stroke, AQP4 facilitates water influx into brain tissue, exacerbating edema." (PMID 39927473, 2025). "Conversely, astrocytes play a role in the development of edema after ischemic stroke onset through aquaporin (AQP4)-mediated water transport." (PMID 40867143, 2025). "In the context of cytotoxic edema (e.g., ischemic stroke), AQP4 facilitates water entry into swollen astrocytes." (PMID 40564125, 2025). "Our study also explored the other possible neuroprotective mechanisms of Neuroncell-EX including angiogenesis (VEGF), maintenance of BBB integrity (AQP4 expression), and neurogenesis (NeuN expression) in the rat model of ischemic stroke." (PMID 40360812, 2025). "Silencing ATF3 significantly decreased the expression of AQP4 and reduced water content in the brain of ischemic stroke rats compared with lv-NC group (p < 0.01), whereas the inhibitory of silencing ATF3 was weakened by anisomycin (p < 0.01)." (PMID 40621504, 2025). "For example, ischemic stroke mainly manifests as cytotoxic cerebral edema, during which AQP4 exacerbates cellular swelling." (PMID 39148543, 2024). "The barrier properties of brain microvasculature are dependent upon the adequate interaction of endothelial cells with astrocyte-endfeet, which was assessed by co-immunolabeling CD31 and AQP4 at the lesion site 1 week after ischemic stroke." (PMID 38769116, 2024). "We found that AQP4 co-localization with CD31+ microvessels at the lesion site was preserved 1 week after ischemic stroke upon PDGF-D increased subacute bioavailability." (PMID 38769116, 2024). "Upregulation of AQP4 can be triggered by a lipopolysaccharide (LPS)-triggered immune response, and heightened levels of AQP4 are thought to be a key mechanism of cellular edema in models of ischemic stroke." (PMID 38988660, 2024). "In a mouse model of ischemic stroke, pathological changes similar to those observed in subarachnoid hemorrhage, including PVS expansion, loss of polarity distribution of AQP4, and astrocyte disorders surrounding ischemic lesions, can be observed." (PMID 38270115, 2024).